CD44 (CD44 molecule (IN blood group))
Diseases named in the same sentence as CD44 in open-access papers (continued):
Sharing a sentence is not in itself a finding about the gene and the disease.
tumor (continued). "The nanoscale delivery system contained a modified polypropyleniminedendrimer as a carrier, paclitaxel, a synthetic analog of luteinizing hormone-releasing hormone peptide for targeting tumor cells, and siRNA targeted to CD44 mRNA." (PMID 25954275, 2015). "Meanwhile, CD44 plays an indispensable role in tumor cell growth, differentiation, invasion and motility in response to a cellular microenvironment, thereby enhancing cellular aggregation and contributing to the development and progression of tumors." (PMID 26010608, 2015). "On endothelial cells, CD44 is known as a marker of tumor angiogenesis, and its adhesion function facilitates endothelial cell migration and sprouting." (PMID 26189059, 2015). "Antisense CD44 inhibited HA binding, tumor growth, and metastasis of colorectal carcinoma cells to the liver." (PMID 26029216, 2015). "CD44 is involved in cell adhesion and migration, lymphocyte activation, extracellular matrix accumulation, and metastasis of tumor cells." (PMID 25929323, 2015). "The CD44+ HPCa52 cells demonstrated higher tumor-regenerating capacity than corresponding CD44− cells." (PMID 26246472, 2015). "A6 has demonstrated activity against CD44-expressing tumor cells and CLL cells, and is a candidate for the treatment of malignant disease and hematological malignancy." (PMID 25870596, 2015). "The oncogenic function of CD44 has yet to be fully established, since CD44 can also act as a tumor suppressor." (PMID 25605020, 2015). "The principal HA receptor, CD44, is widely expressed in mammalian tissues and has been shown to have important roles in inflammation, tumor progression, embryogenesis, and immune cell activation as well as fibrosis (16, 37, 56, –, 58)." (PMID 25716319, 2015). "They found that CD44 was highly expressed in almost 50% or RCC and was associated with tumor grade, size and stage." (PMID 28031890, 2015). "As in the case of HA-coated nanoparticles or liposomes, anti-CD44 antibody–drug conjugates have also been used either for imaging of tumors or for delivering chemotherapeutic agents to experimental tumor models." (PMID 25954275, 2015). "Tumor-derived cells express CD44 in a high-affinity state that is capable of binding and internalizing HA." (PMID 25999946, 2015). "In pancreatic ductal adenocarcinoma, tumour cells with the CD44+CD24+ESA+ immunophenotype convey the properties of self-renewal and multilineage differentiation and are thus considered the pancreatic CSC population." (PMID 26270676, 2015). "Instead of interfering with the function of CD44 proteins, these studies have aimed at inhibiting CD44 expression in tumor cells." (PMID 26569327, 2015). "With the thoroughly research in the mechanism and regulation pathway, CD44 will play a greater role in tumor diagnosis, treatment, and prognosis." (PMID 26666511, 2015). "The expression of CD44, CHI3L1 and ITGA6 are all associated with EMT, which were scarcely detected in the AOI as compared to their elevated expression at the tumor core." (PMID 25365423, 2014). "The binding of CD44 and its ligands was essential in regulating the adhesion of tumor cell with platelets, leucocytes, sinusoidal endothelial cells and stellate cells, therefore was considered critical in liver metastases." (PMID 25551689, 2014). "CSCs show activation of epithelial to mesenchymal transition (EMT) programming and acquire a basal-like CD44+/CD24low/− phenotype with increased capacity for self-renewal, invasion, drug resistance and tumor progression." (PMID 24970653, 2014). "CD44 is involved in various cell adhesion events, including lymphocyte migration, hematopoiesis, and tumor metastasis." (PMID 25330516, 2014). "In contrast a significant increase in expression of CD24, CD34, CD44 and Oct4 was observed in tumor extracts from animals treated with CIS (6 mg/kg) as compared to mock-treated mice or mice treated with WFA (2 mg/kg) alone." (PMID 25264898, 2014).
tumor (continued). "Reduction of CD44 on tumor cells rendered inhibition of Matrigel invasion by these cells, and arazyme-treated tumor cells showed reduced lung colonization after endovenous inoculation." (PMID 24788523, 2014). "CD44, a hyaluronic acid receptor, is one of the most commonly studied surface markers, which is expressed by almost every tumor cell." (PMID 25161776, 2014). "Ectopic expression of miR-34a either in prostate cancer cells or in the CD44+ fraction leads to inhibition of clonogenic expansion, tumor regeneration, and metastasis in vivo." (PMID 24657911, 2014). "This discrete expression pattern was also observed in dissociated primary tumor cells that were stained for CD44 and CD271 and analyzed by flow cytometry." (PMID 25149537, 2014). "CD44 is thought to be involved in the signature of tumor-initiating cells from the analyses of several solid carcinomas such as colon carcinomas, head and neck carcinomas, non-small cell lung cancer, hepatocellular carcinoma, and breast cancer." (PMID 24727741, 2014). "Further experiments validated that the tumor-suppressive and chemosensitivity effect of miR-34a was mediated by reducing the production of CD44." (PMID 24423412, 2014). "CSC can be identified and isolated using various markers and CD44 expressing tumor cells isolated from HNSCC were identified as CSC based on increased clonogenic potential and tumor-forming ability." (PMID 25340704, 2014). "Nestin is also involved in regulating the Wnt effector; the CD44 gene, a known putative cancer stem cell marker involved in mediating tumor cell metastasis." (PMID 24625091, 2014). "It has been reported that highly expressed CD44 in certain types of tumors is related to the hematogenic spread of tumor cells." (PMID 24949469, 2014). "FACS analysis of tumor cells from MMTV mice (long-term treatment) for CD44+Sca1+ cell population also confirmed that CSC population was substantially decreased after Sac-1004 treatment." (PMID 24811731, 2014). "We found high percentages of ALDH cells co-expressing CD44 in the ALDHhigh fractions of H28 (59.7%), H2052 (51.6%) and Meso4 (69.5%) relative to all tumour cells." (PMID 24884875, 2014). "Some studies have shown that the CD44+ cells are enriched for tumor-propagating capacity and that CD44 is a potential CSC marker in NSCLC." (PMID 24595209, 2014). "Level of staining intensity was compared to clinical and pathological characteristics of tumors with the aim to identify impact of CD44 or CD133 expression on tumor behavior." (PMID 24864242, 2014). "Expression of miR-34a in CD44+ PCa cells inhibits tumor migration and metastasis in a xenograft model, and miR-34a inhibits Notch and AR signaling in PCa cells, suggesting that miR-34a suppresses the self-renewal activity of CSCs in PCa cells." (PMID 24427168, 2014). "The cytostatic effect of arazyme, reduction of CD44 molecules although with normal CD44 mRNA expression, and reduction on cell adhesion in vitro was also seen on human tumor cells." (PMID 24788523, 2014). "Among the various CD44 isoforms, the V6 exon-containing isoforms (CD44V6) have been implicated in tumorigenesis, tumor cell invasion and metastasis." (PMID 24173428, 2014). "CD44 was positive in 57 tumor samples (60 %) whereas CD133 was positive in 47 tumor samples (49.5%)." (PMID 25635255, 2014). "Despite its regulation in many cellular processes, CD44 plays a crucial role in tumor cell differentiation, invasion, and metastasis." (PMID 24699672, 2014). "Of the unique mAbs generated, we examined those binding CD44 in detail due to the importance of this antigen in tumor biology." (PMID 25353955, 2014). "Over 80% of ALDH+ CD44 cells developed into a tumor at a dose 10 times lower than that of ALDH-CD44-Lin cells when implanted in mice." (PMID 24348811, 2014).
tumor (continued). "CD44 promotes tumor progression through the activation of low molecular weight hyaluronan, which in turn activates signaling pathways promoting cell migration and invasion, or by acting as a co-receptor to oncogenes (c-Met and ErbB receptors)." (PMID 24760019, 2014). "CD44 has been recognized to recruit and accumulate matrix metalloproteinase on the cell surface, enabling indirectly tumor cell angiogenesis and invasion." (PMID 25309869, 2014). "Proteases have been shown to influence the expression of adhesion molecules on tumor cell surface, and one of such molecules, CD44, is highly expressed in tumor cells." (PMID 24788523, 2014). "Recent studies have identified CD44+EpCAMhigh cells as the tumor cell populations harboring CSC properties (self-renewal and aberrant differentiation) in CRC, which drive tumorigenic events." (PMID 25294814, 2014). "There are two possible explanations for the presence of CD24+/CD44+ tumor cells from CD24-/CD44+ tumors." (PMID 24612587, 2014). "The literature suggests that CD44 high tumour cells display increased self-renewal, migration and therapy resistance and are suggested to be cancer initiating cells (CIC)." (PMID 25230021, 2014). "CD44 is also expressed in tumor stem cells that have the unique ability to initiate tumor cell-specific properties." (PMID 24606718, 2014). "Because the EMT has been shown to endow tumor cells stem-like properties 31,32, we next assayed the surface expression of CD44 and lgr5, which have been shown to be specific markers of GCSPCs 33–35." (PMID 25142304, 2014). "Although CD44 proteins are involved in the regulation of various cellular processes, CD44 has been indicated to play a pivotal role in tumor cell differentiation, invasion, and metastasis." (PMID 24971320, 2014). "TNBC tumors recurrence following treatment with PARP-inhibitors can be explained by recent studies demonstrating that PARP-inhibitors eliminate the bulk of tumor cells, but they have limited ability to eliminate CD44+/CD24− CSCs." (PMID 24970653, 2014). "After enzyme removal, CD44 de novo synthesis reconstitutes its surface expression, and cell cycle resumes after tumor cell adhesion." (PMID 24788523, 2014). "Using flow cytometry, we sorted the tumor-retrieved cells into four subgroups and further analyzed the specific role of the Sca-1+-CD44+ MSCs in tumor progression." (PMID 24581230, 2014). "CD44, a well-known tumor marker, plays a crucial role in tumor cell differentiation, invasion, and metastasis." (PMID 24699672, 2014). "In order to test if ZsGreen-cODCpos cells in HNSCC overlap with cells positive for other established CSCs markers, HNSCC tumor sections were stained against CD44." (PMID 24593279, 2014). "Positive expression of CD44, either individually or combined with other markers, has been observed in cells involved in tumor progression and metastasis, and these cells have been suggested to be cancer stem cells (CSCs)." (PMID 24971320, 2014). "These cells, known as cancer stem-like cells or tumor initiating cells (TICs), have been observed in other cancers including prostate, pancreatic, brain and leukemia, making CD44 an important target for cancer therapies." (PMID 25184276, 2014). "CD44, one of the well-known tumor markers, plays an essential role in tumor cell differentiation, invasion, and metastasis." (PMID 24971320, 2014). "CD44 protein levels were decreased in cells over-expressing miR-34a, and knock down of CD44 functionally mimicked the miR-34a effects of inhibition of tumor development and metastasis." (PMID 25212506, 2014). "Consistent with our findings in mice, Mo-MDSC increased the ALDH1Bright and CD24+, CD44+ CSC population in BxPC3 after coculture as compared to control tumor cells." (PMID 24652403, 2014).
tumor (continued). "Low levels of the hyaluronic acid receptor CD44 are found on the surface of epithelial, hematopoietic, and neuronal cells; it is overexpressed in many cancer cells, and in particular in tumor-initiating cells." (PMID 24642908, 2014). "So far, CD44 expression on cancer cells has been shown to regulate multiple aspects of cancer cell phenotypes, modulating tumor proliferation, migration, invasion, and angiogenesis." (PMID 24122205, 2014). "HA binding to CD44 not only affects cell adhesion to the matrix but also stimulates several tumor-specific functions." (PMID 24725816, 2014). "In human Huh-7 cells, Ad-PTEN gene delivery suppressed PGE2-induced Akt activation, CD133/CD44 up-regulation and tumor sphere formation." (PMID 24721996, 2014). "Investigations of CD44 over the past 20 years have established additional functions for CD44, including its capacity to mediate inflammatory cell function, tumor growth, adhesion, migration and metastasis." (PMID 25112408, 2014). "The protein expression of RRM2 was also positively and significantly associated with CD44+/CD24-/low, a tumor stem/progenitor cell biomarker." (PMID 25213022, 2014). "Subpopulations of tumor initiating cells from HNSCC are currently defined by their high expression of CD44 and BMI1 along with their high ALDH activity." (PMID 25471937, 2014). "None of the aptamers stained SK-Br-3 cells, suggesting that the DNA aptamers recognize CD44 exon v10 on the tumor cell surface of HCC38 cells." (PMID 24586375, 2014). "Our observation that inhibition of tumor growth in SCID mice by the combination of metformin and FuOx is associated with reduction in CD44 levels and colonosphere forming ability in cells derived from xenograft of CR cells indicates reduction in CSCs/CSLCs." (PMID 24465408, 2014). "Our results suggest a novel model of molecular complex consisting of CD44 and EphA2 that promote of tumor progression and metastasis." (PMID 24586375, 2014). "Seemingly, the reversible cytostatic effect of arazyme on B16F10-Nex2 cells involves proteolysis of CD44 that reduces the adhesion of tumor cells to the matrix substrate." (PMID 24788523, 2014). "ADAM17 is involved in the cleavage of numerous surface molecules, most of which are considered to be relevant in tumour-associated processes such as cell growth, migration and invasion (TNF-α, CD44, L1-CAM, L-selectin, ICAM1, CX3CL1, etc.)." (PMID 25246708, 2014). "Prostate CSCs with tumor initiating and metastatic potential are enriched in the CD44+ subpopulation." (PMID 24657911, 2014). "Restoring miR-34a expression inhibits clonogenic expansion, tumor development and metastasis by targeting CD44 expression." (PMID 25019555, 2014). "CD44 overproduction appeared to have a dramatic positive effect on tumor cell growth and tumorigenesis, and importantly, miR-34a induced tumor suppression was largely eliminated upon the overexpression of CD44." (PMID 24423412, 2014). "Expression of the hyaluronan cell surface receptor CD44 has also been shown to be increased in tumor cells." (PMID 24133067, 2014). "CD44 plays a major role in many physiological processes, including cell substrate, interaction cell-cell adhesion, lymphocyte homing, and tumor metastasis." (PMID 24949469, 2014). "Invivo however, FACS of tumor cells of 3 mice after the end of the experiment showed a marked decrease in CD44 expression with SGK-1 inhibition." (PMID 25485633, 2014). "In order to investigate the effects of the different treatment modalities on malignant potential and propensity towards worse outcomes, we subjected tumor cells to FACS analysis of CD44, a marker for cancer-initiating cells." (PMID 25485633, 2014). "To estimate the proportion of CD44high/CD24low cells, we characterized tumor-derived cell lines by flow cytometry for surface expression of CD44 and CD24, respectively." (PMID 25361000, 2014).
tumor (continued). "CD44 plays a vital role in the regulation of cell adhesion, growth, differentiation, migration and angiogenesis, and contributes to tumor progression by promoting invasion and metastasis." (PMID 24765173, 2014). "By FACS of fresh tumor biopsies, we isolated the CD44+/CD24- subpopulation from one tumor and ALDH1High cells from a second tumor." (PMID 24998755, 2014). "Because of the intense crosstalk between the molecules that compose the ECM and the effects on tumor regulation, different therapeutic approaches have been used targeting members of the integrin family, CD44 and MMPs." (PMID 24788523, 2014). "Different tumor cells have high expression of CD44, which plays a critical role in tumor progression, because degradation of HA facilitate tumor cell invasion and the spread of cancer." (PMID 24788523, 2014). "In support of our results, So et. al. reported that an analogue of vitamin D3 (BXL0124) represses the expression of the stem cell marker CD44 in vitro and also decreased tumor growth of a xenograft in vivo." (PMID 25460500, 2014). "In vitro, arazyme showed a dose-dependent cytostatic effect in B16F10-Nex2 cells, reducing cell adhesion by reducing CD44 molecules on tumor cell surface." (PMID 24788523, 2014). "We evaluated the relationship between markers expression in primary and secondary tumor and tested the impact of CD44 and CD133 positivity on clinical behavior of tumor, mainly on overall survival and disease free interval." (PMID 24864242, 2014). "CD24 and CD44 expression levels were also analyzed according to age, sex, tumor differentiation, depth of invasion, lymph node metastasis, and TNM stage." (PMID 25212506, 2014). "The ability of let-7 to inhibit tumor initiation was first demonstrated in a murine CD44-positive xenograft model, where overexpression and therapeutic injection of let-7 resulted in delayed tumor formation." (PMID 25250334, 2014). "Experiments in animals have shown that targeting of CD44 by antibodies, antisense oligonucleotides, and CD44-soluble proteins markedly reduces the malignant activities of various neoplasms." (PMID 24595031, 2014). "They demonstrated that forced expression of miR-34a reduces purified CD44+ stem-like prostate cancer cells and that it is sufficient to inhibit clonogenic expansion, tumor regeneration, and metastasis." (PMID 25309903, 2014). "CD133 expression in CRC and CLM differed based on CRC grading; in case of CD44 we found differences in staining intensity in individual stages of tumor lymph node invasion." (PMID 24864242, 2014). "CD44 and EpCAM, known to be present in a variety of tumor entities, were also expressed in tumor and lung metastases to a high degree." (PMID 24699516, 2014). "CD44 has been described previously as both a tumour suppressor and an oncoprotein in various cancers, which highlights a complex and probably tissue-specific role in oncogenesis." (PMID 24512624, 2014). "An interesting aspect of our case consists of evident overexpression of CD44 in squamous component of neoplasia, with spreading positivity in the perineoplastic stroma cells." (PMID 24959179, 2014). "All these data presented here strongly suggesting that the tumor-suppressive and chemosensitivity effect of miR-34a was mediated by reducing the production of CD44 as its predominant target." (PMID 24423412, 2014). "CD44 is the major hyaluronan (HA) receptor, and CD44 bound to HA has been proven to participate in various tumor biological activities, including tumor progression, metastasis and proliferation." (PMID 24410905, 2014). "Only a small subgroup of the tumor cell population is responsible for tumor invasion and renewal potential, also referred to as cancer stem cells (CSCs), which express cell surface markers such as CD44, CD166, CD133 and ALDH1." (PMID 24404205, 2014).